LGR5 (leucine rich repeat containing G protein-coupled receptor 5)
Diseases named in the same sentence as LGR5 in open-access papers (continued):
Sharing a sentence is not in itself a finding about the gene and the disease.
tumor (continued). "However, it is possible that other tumor models may require Lgr5 function, and this would need to be evaluated on a case-by-case basis." (PMID 28649656, 2017). "In IHC, multivariate analyses demonstrated that Lgr5, CD133 and EpCAM were independently related to old age, CD133 and Sox2 were independently associated with well or moderate differentiation, while Oct4, CD133 and EpCAM were independently related to tumor progression." (PMID 27557490, 2016). "In addition, LGR5 depletion significantly inhibited tumor orthotopic xenograft growth in nude mice." (PMID 24172981, 2014). "In addition, tumor growth in vivo was also suppressed by LGR5 siRNA." (PMID 24789370, 2014). "Therefore, down-regulating LGR5 could attenuate tumor initiation and tumor progression in SiHa cells." (PMID 25193857, 2014). "Thus, in this cellular context LGR5 functioned more as a tumor suppressor than tumor promoter." (PMID 23596566, 2013). "Notably, in the GA with a basal pattern, LGR5 expression was confined to the very lower area of the tumor glands when other stem cell markers were expressed by a larger population of cells beyond the base, suggesting that LGR5 is a marker for a specific group of cells with stem cell features." (PMID 24340024, 2013). "Thus, it remains unknown whether Lgr5+ cells retain their stem cell characteristics during tumor progression." (PMID 24340024, 2013). "Since the spatial distribution of LGR5+ cancer cells and hence the putative stem cell niche may be important for its tumour biological significance, we investigated each compartment, i.e. luminal surface, tumour centre and invasion front, separately." (PMID 22530031, 2012). "Thus, we hypothesized that LGR5 mRNA expression in PB of CRC patients could indicate the presence of circulating tumor cells with stem cell properties." (PMID 22605983, 2012). "The difference in tumour size between the LGR5 knockdown and the parental cells was highly significant (p<0.0001) at all time points, however the growth of tumours overexpressing LGR5 differed significantly from parental cells only for the first 10 days of the xenografts experiment." (PMID 21829496, 2011). "Therefore targeting of LgR5 signalling might be a potential mechanism to abrogate this inflammation-mediated effect in tumor progression." (PMID 21345220, 2011). "We found that RSPO4 FUm1/2 mutant lost its inhibitory effect on migration and invasion of both LGR4+/LGR5- and LGR4-/LGR5+ tumor cells." (PMID 41522353, 2026). "LGR5, ALDH1, CD44, and CD133 are critical CSC markers for tumor growth, metastasis, and therapy resistance." (PMID 41438576, 2026). "Consistently, luciferase reporter assay showed that RSPO4 FUm1/2 mutant lost the inhibitory effect on Wnt/β-catenin signaling and target genes in both LGR4+/LGR5- and LGR4-/LGR5+ tumor cell lines." (PMID 41522353, 2026). "Specific inhibitors of IL-17RA signaling, such as the STAT3 inhibitor Stattic, reduced the expression of CD133, LGR5, ALDHA1, SOX2 and c-MYC, as well as tumor sphere formation in SW620 cells." (PMID 41438576, 2026). "It was found that GATA6 directly drove the expression of LGR5 in adenoma stem cells, but restricted BMP signalling to differentiated tumour cells." (PMID 40212011, 2025). "This subtype exhibited significant stem cell-like characteristics, marked by the high expression of key stemness genes such as EZH2, LGR5, NOTCH1, and ABCG2, which together formed a core regulatory network maintaining tumor stem cell properties." (PMID 40787449, 2025). "A significant positive correlation between LGR5 and Ki-67 (proliferation marker) expression was observed in the CRC tumor tissues (r2=0.680, p<0.001)." (PMID 39821694, 2025). "Then we separated tumor cells into LGR5+ and LGR5- clusters, revealing significantly higher ALKBH5 expression in LGR5+ cells compared to LGR5- cells." (PMID 41390849, 2025).
tumor (continued). "The resultant α-LGR5scFv CAR T cells exhibited potent and specific killing of LGR5-overexpressing cells as well as LGR5+ pre-B ALL, CRC, and HCC tumour cell lines." (PMID 40405910, 2025). "In CRC, several CSC-specific markers, such as leucine-rich repeat-containing G-protein-coupled receptor 5 (LGR5), CD44, and CD133, have been identified as indicators of tumor aggressiveness and poor clinical outcomes." (PMID 40429879, 2025). "The neoplasm showed high expression levels of LGR5 (stem cell marker gene, investigated as a therapeutic target in CRC), FN1 (extracellular matrix remodeling), and TGFBR2 (conditional tumor suppressor/activator as part of TGF signaling)." (PMID 40667282, 2025). "Consequently, more effective cancer therapy may be achieved by dual targeting of the LGR5- and LGR5+ cell populations to address both the LGR5- tumor bulk and initial metastatic seeding, and the LGR5+ cells that drive the growth of primary cancers and metastases." (PMID 40427162, 2025). "proCSCs are highly proliferative, LGR5+, OLFM4+, and LRIG1+ drive tumor expansion, whereas revCSCs, also referred to as plastic persisters, are slow-cycling, CLU+, drug-resistant, and prioritize survival over proliferation." (PMID 41002429, 2025). "The expanding landscape of ADC targets in CRC now includes not only antigens on bulk tumor cells (CEACAM5, HER2), but also those on cancer stem cells (LGR5) and critical stromal components (CEACAM6), offering multiple avenues to dismantle the tumor ecosystem." (PMID 41256852, 2025). "LGR5+ cells enhanced WNT/β-catenin pathway and detachment of tumor cells which migrate to nearby lymph nodes." (PMID 39821694, 2025). "For instance, MCLA-158 (petosemtamab), a BsAb targeting both EGFR and LGR5, exhibited strong growth inhibition of patient-derived CRC organoids and orthotopic xenograft tumor models, including KRAS mutant CRCs resistant to cetuximab." (PMID 40076613, 2025). "Preclinical 3D co-culture models combining murine LGR5+ Liver-CSCs with CAFs have demonstrated CAF-mediated amplification of Liver-CSC self-renewal and tumor-initiating capacity." (PMID 41438763, 2025). "To model the process of residual tumor cells transitioning to recurrence after chemotherapy, we established an in vitro regrowth model using a CCD-organoid derived from LGR5-positive PLR123 CRC cells." (PMID 40537472, 2025). "We provide a comprehensive overview of the ADC landscape, examining key targets on bulk tumor cells (CEACAM5, HER2), cancer stem cells (LGR5, GPR56), and stromal components." (PMID 41256852, 2025). "FMRP interacts with both GSK3β and CTNNB1, MSI1 represses APC and enhances Wnt signaling in epithelial progenitors, while MEX3A stabilizes LGR5 and represses DKK1, thereby promoting stemness and tumor progression." (PMID 41516083, 2025). "The intersection of LGR5+ and LAPTM4B+ stem‐like cells provide a basis for CRC stratification, leading to the CSS classification, which delineates four tumor subtypes with distinct biological and clinical attributes." (PMID 40661135, 2025). "LGR5 expression was dramatically reduced following treatment with either 5μM or 10μM 4-AAQB in colon cancer cells (HT29, HCT116) and inhibited tumor growth in vivo." (PMID 39821694, 2025). "Upregulation of miR-142-3p suppressed growth of CRC cells and xenograft tumor by downregulating CD133, ABCG2, and Lgr5, CDK4, and CTNNB1." (PMID 40868120, 2025). "It induces core stemness regulators (DCAMKL-1, LGR5, CD133, AFP, CK19, Lin28, c-MYC), establishing chemoresistant tumor-initiating phenotypes." (PMID 41438763, 2025). "In Cohort IV, which included paired CRC tumor and adjacent normal tissues (N = 12), we consistently found positive correlations between the protein expression of YTHDF1 and that of CD133 and LGR5." (PMID 41423446, 2025). "(M) Representative in situ hybridization (ISH) staining of tumor sections from ApcMin/+, BC, and FBC mice using Lgr4 and Lgr5 probes." (PMID 38921956, 2024).
tumor (continued). "The high expression of LGR5 and LGR6 mRNA in HGSOCs allows them to be constantly stimulated by WNT signaling, which leads to uncontrolled cell growth and tumor development." (PMID 40836974, 2024). "We firstly analyzed the correlation between the expression of TRIM71 and tumor stem cell markers in HCC and HB and found significant positive correlation between TRIM71 and CD133, CD24, EPCAM, and LGR5 in HCC and HB tumor samples." (PMID 39267787, 2024). "Our pilot study results demonstrate the presence of LGR5- and CD90-positive tumor cells in all samples." (PMID 39727953, 2024). "α-LGR5-ADC was the most effective modality for targeting LGR5+ cancer cells in vitro and demonstrated potent anti-tumour efficacy in a murine model of human NALM6 pre-B-ALL driving tumour attrition to less than 1% of control treatment." (PMID 39169164, 2024). "Both normal and tumor tissue were examined for γ-H2AX, p16, and Lgr5-GFP expression through immunostaining." (PMID 39410012, 2024). "In particular, we demonstrate an MACC1—LGR5 link by transcriptional regulation of the crucial stemness gene LGR5 by MACC1, the inducer of tumor initiation, progression and metastasis." (PMID 38339354, 2024). "The characteristic punctate distribution of LGR5 we observe in LoVo and NALM6 cells is consistent with our observations in CRC and HCC tumours." (PMID 39169164, 2024). "Two LGR5-targeting ADCs (LGR5–MC-vc-PAB–MMAE and LGR5–NMS818) were developed by MedChemExpress to target LGR5-positive tumor-initiating cells and cancer stem cells." (PMID 39065798, 2024). "Tumorigenesis and increased tumor volumes were observed in those mice transplanted with CD44-high/CD166+ cells also showing high MACC1 and LGR5 levels (vs. CD44-low/CD166+ cells)." (PMID 38339354, 2024). "Meanwhile, co-culture with NK cells upregulated the expression of KI67, a sign of proliferation for tumor malignancy, and stemness markers CD90, CD44, LGR5, and NANOG in CRC cells." (PMID 38543173, 2024). "The results of this pilot study demonstrate the presence of LGR5- and CD90-positive tumor cells in ACC, confirming the importance of studying CSC markers in both basic and clinical research." (PMID 39727953, 2024). "However, LGR5 expression may be affected by the tumor microenvironment." (PMID 38787285, 2024). "The obtained results demonstrate the presence of LGR5- and CD90-positive tumor cells in all samples." (PMID 39727953, 2024). "α-LGR5-CAR-T cells also showed specific and potent LGR5+ cancer cell killing in vitro and effective tumour targeting with a fourfold decrease in pre-B-ALL tumour burden relative to controls." (PMID 39169164, 2024). "Dinaciclib decreased LGR5 and ID1 expression levels and exhibited higher tumor growth suppressing effects than that of THZ531." (PMID 38182897, 2024). "The average DAB pixel density for the spontaneous tumor tissue was 10.5 ± 2.04 (mean ± SEM), γ-rays 6.7 ± 0.64 (mean ± SEM), and 56Fe 5.0 ± 0.98 (mean ± SEM), also indicating a decreasing trend in LGR5 expression after radiation exposure." (PMID 37686516, 2023). "Various authors have described the main CSCs markers of CRC, such as LGR5, CD133, and CD44, by identifying them from CRC tumours and testing the different subpopulations that exist within the tumour." (PMID 36835258, 2023). "To assess the link between mTORC1, refeeding, and tumour initiation in ISC, we administered rapamycin to AL and refed Apcloxp/loxp: Villin-CreERT2 and Apcloxp/loxp; Lgr5-EGFP-IRES-CreERT2 mice." (PMID 36711807, 2023). "Our observations support the proposed role of YAP as a tumor suppressor in metastatic CRC, where it can inhibit the Wnt pathway by reprogramming LGR5+ cells and, in vivo, by reducing Wnt activity." (PMID 36460033, 2023). "Tumor cells isolated from Id1Lyz-KO group expressed lower CD44 and Lgr5 (CSC marker) than those from Id1f/f group." (PMID 37996458, 2023).
tumor (continued). "First, tumor organoids isolated from LGR5‐GFP‐creERT/Rosa26‐iDTR transgenic mice were digested into single cells and LGR5‐expressing tumor cells were sorted out by flow cytometry based on GFP expression." (PMID 37578396, 2023). "HCT116 cells cocultured with CRC patient’s tumor tissues derived ID1KD TAMs expressed lower levels of CD44 and LGR5 than those cocultured with Ctrl TAMs." (PMID 37996458, 2023). "Evidence has shown that the tumorsphere- and colony-forming ability of tumor cells is regulated by the stemness of tumor cells and the enhanced stemness of CSCs is often closely related to the abnormal expression of CD44, CD24, CD133, and Lgr5." (PMID 37005676, 2023). "Immunohistochemistry (IHC) staining was performed using (i) PD-L1 antibodies to detect PD-L1 expressions; (ii) CD8 and CD4 to detect Tumor Infiltrating Lymphocytes (TILs); and (iii) CD44, LGR5, and ALDH2 to detect stem cell markers." (PMID 36604635, 2023). "We have previously shown that Lgr5 high/wnt high/L1CAM low and Lgr5 low/wnt low/L1CAM high cells have distinct roles with the former being important for homeostasis and sporadic CRC tumor initiation and the latter for regeneration and metastasis." (PMID 36611031, 2023). "In gastric cancer, B7-H1 expressed in Lgr5+ gastric CSCs can enhance CSC proliferation and tumor formation by binding with PD-1 on T cells." (PMID 36910604, 2023). "A comparison of WNT5A and LGR5 protein expression in morphologically normal and cancer tissue patients revealed that normal tissue has a significantly higher WNT5A IRS than tumor tissue." (PMID 37998393, 2023). "In T2-T3 stage CRC, CD90+ CAFs are the main source of IL-6 in the tumor microenvironment and can promote the expression of stem cell markers ALDH and Lgr5 in cancer cells, thereby promoting cancer development." (PMID 37124519, 2023). "Regarding the analyzed patient samples, more than half of tumor cells acquired stem cell-like features with markers such as CD44, CD133, and Lgr5." (PMID 35844581, 2022). "Strikingly, markers of normal colon stem cells (LGR5, ASCL2, SOX9), were also strongly downregulated EHFlow CRC cells, suggesting that these lines give rise to tumours that are de-differentiated to the point of losing their colonic identity." (PMID 35606410, 2022). "Tumors displayed an undifferentiated morphology, were positive for the NB marker PHOX2B, and maintained high amounts of MES markers SOX9 and LGR5 along with low ADR marker TH, in concordance with the parental relapse tumor." (PMID 36306349, 2022). "Using various experiments, we proved that the inflammatory condition-induced high LGR5 expression in FaDu cells and LGR5 overexpression lead to the hyperfunction of YAP/TAZ and enhanced proliferation, migration, and invasion of tumor cells." (PMID 36288272, 2022). "Therefore, we believe that the inflammatory condition causes high LGR5 expression, which will inhibit the phosphorylation of YAP, resulting in markedly increased YAP-TEAD binding, high expression of EMT-related proteins, and enhanced invasion and metastasis ability of tumor cells." (PMID 36288272, 2022). "Primary CRCs and macrometastases exhibited similar distribution of cell populations, including proliferative cells, Lgr5+ ISC-like cells, Krt20+ differentiated tumor cells and HRCs, most of which were also Krt20+." (PMID 36352230, 2022). "This cell population gave rise to Lgr5+ ISC-like and proliferative tumor cell progeny, which are abundant in small metastases." (PMID 36352230, 2022). "In conclusion, we have demonstrated for the first time that the inflammatory condition can lead to high LGR5 expression in HSCC, and high LGR5 expression can promote the proliferation and invasion of tumor cells by inhibiting the phosphorylation of YAP." (PMID 36288272, 2022).
tumor (continued). "Proliferative tumours were characterized by high expression of the c-MET, ARID1A, CTNNB1, RAF1, LGR5, and GLUL1 genes." (PMID 36345011, 2022). "LGR5 and CD44 staining in colonic crypt cells and tumor epithelia showed that AOM/DSS induced tumor formation." (PMID 35269806, 2022). "Remarkably, multivariate analysis demonstrated that epithelial LGR5 expression (P = 0.018) is an independent prognostic marker along with FIGO stage (P = 0.033) and the presence of residual tumor after operation (P = 0.047)." (PMID 35778589, 2022). "To assess the role of Lgr5+ tumor cells in our relapse models, we knocked-in a DTR cassette into the Lgr5 locus of AKTP MTOs." (PMID 36352230, 2022). "We detected the expression of IL-17RB, Lgr5, and CD90 in single tumor cells purified from GC tissues through flow cytometry." (PMID 33649532, 2021). "Expression study of LGR5, HES1 and ATOH1 were performed by quantitative PCR (QPCR) based on comparative Cq method after normalization to adjacent non tumor tissues and ACTB as a reference gene." (PMID 34582650, 2021). "We provide evidence here of a reduction in tumor stemness characteristics as seen by reduced Lgr5 and Smoc2 in both CAC and Apcmin/+ models, as well as in tumor organoids derived from both models." (PMID 34710062, 2021). "The study detected overexpression of LGR5 and HES1 and down-regulation of ATOH1 in human RC tissues compared to non- tumor tissues." (PMID 34582650, 2021). "A significant increase was observed in the expression of LGR5 (p: 0.0002) and MYC (p: 0.002) genes in G2 stage tumor tissues (group 9) compared to the control group." (PMID 34452555, 2021). "Consistent with reprogramming to liver and tumor cells, respectively, the clonal line expressed endogenous HNF4A, and high levels of the Wnt pathway modulator and stem cell marker LGR5." (PMID 34302118, 2021). "In this model, short-term ablation of LGR5+ cells, in combination with anti-EGFR therapy, elicited a more pronounced inhibition of tumour growth than either treatment alone." (PMID 33673710, 2021). "Validating these findings, we found expression of canonical WNT target genes AXIN2, LGR5, TCF7 and ASCL2 were elevated in tumours expressing high levels of RAC1B." (PMID 33879799, 2021). "As observed in spheroids, clustering of cells from LGR5+ PDO, PDX, and primary tumor cells revealed subpopulations of stem-like, TA-like, or Tdiff-like cells." (PMID 33806447, 2021). "A significant increase was observed in the expression of LGR5 (p: 0.01) and PROM1 (p: 0.005) genes in villous HGD polyps, LGR5 (p: 0.003) gene in G1, and LGR5 (p: 0.0002) and MYC (p: 0.002) genes in G2 stage tumor tissues." (PMID 34452555, 2021). "Collectively, these results suggest that LGR5+ALDH1+OCT4High AM epithelial cells demonstrate increased self-renewal capability and represent a subpopulation of tumor epithelial stem-like cells in solid AM (AM-EpiSCs)." (PMID 32382005, 2020). "To date, the clinical importance of LGR5 for BC remains largely unexplored outside of two clinical studies that have correlated LGR5 with TNBC and with tumor size and lymph node metastasis." (PMID 32522170, 2020). "Some studies have shown that aberrant activation of Wnt/β‐catenin in LGR5+/PROM1+/BMI‐1+ CSCs is important for CRC tumorigenesis and tumor progression in murine models." (PMID 31788944, 2020). "Co-expression of Lgr5 and Ido1 mRNA was barely detectable by ISH in Stat1flox/floxApcMin tumor cells, indicating that IDO1+ cells are Paneth cells." (PMID 32444775, 2020). "In a subset (Lgr5+) of crypt stem cells, gain of YAP surprisingly displays a tumor-inhibitory role via its cytoplasmic sequestration of disheveled 2 (DVL 2) or by inhibiting the activity of the TCF transcriptional complex." (PMID 32540914, 2020).